DTD1 (D-aminoacyl-tRNA deacylase 1)
Description:
Possible ATPase involved in DNA replication, may facilitate loading of CDC45 onto pre-replication complexes. An aminoacyl-tRNA editing enzyme that deacylates mischarged D-aminoacyl-tRNAs. Also deacylates mischarged glycyl-tRNA(Ala), protecting cells against glycine mischarging by AlaRS. Acts via tRNA-based rather than protein-based catalysis; rejects L-amino acids rather than detecting D-amino acids in the active site. By recycling D-aminoacyl-tRNA to D-amino acids and free tRNA molecules, this enzyme counteracts the toxicity associated with the formation of D-aminoacyl-tRNA entities in vivo and helps enforce protein L-homochirality.
Synonyms: DTD; DUE-B; C20orf88; DUEB; HARS2; MGC119131; MGC41905; bA379J5.3; bA555E18.1; pqn-68
Tractability: Small molecule: it has a binding pocket of medium quality. PROTAC: ubiquitination databases record sites on it; its protein half-life has been measured.
Target class: Enzyme; Hydrolase
Gene: Protein-coding gene on chromosome 20 (18,587,920 to 18,766,644, forward strand). Ensembl gene ENSG00000125821.
Subcellular location: Nucleus; Cytoplasm
Subcellular location (Human Protein Atlas): Cytosol; Nucleoli
Gene Ontology:
Molecular function: DNA binding; D-aminoacyl-tRNA deacylase activity; D-tyrosyl-tRNA(Tyr) deacylase activity; Gly-tRNA(Ala) deacylase activity; aminoacyl-tRNA deacylase activity
Biological process: tRNA metabolic process; aminoacyl-tRNA metabolism involved in translational fidelity
Cellular component: mitochondrion; cytoplasm; nucleus
Genetic constraint (gnomAD): Loss-of-function variants: 12 observed, 24.04 expected, observed/expected ratio (o/e) 0.5, 90% interval 0.32 to 0.81. The upper end of that interval is the gene's LOEUF score, 0.81, which puts it in group 3 of 6, group 1 being the genes least tolerant of losing a copy. Missense variants: 192 observed, 262.56 expected, observed/expected ratio (o/e) 0.73, 90% interval 0.65 to 0.82. Synonymous variants: 110 observed, 105.35 expected, observed/expected ratio (o/e) 1.04, 90% interval 0.89 to 1.22.
Homologues: Orthologues: pig DTD1 (96% identical), rabbit DTD1 (96% identical), mouse Dtd1 (95% identical), guinea pig DTD1 (92% identical), chimpanzee DTD1 (88% identical), dog DTD1 (82% identical), tropical clawed frog dtd1 (81% identical), macaque DTD1 (80% identical), zebrafish dtd1 (76% identical), rat Dtd1 (67% identical), Drosophila melanogaster Dtd (45% identical), Caenorhabditis elegans pqn-68 (40% identical). Paralogues in human: DTD2 (20% identical).
Diseases named in the same sentence as DTD1 in open-access papers:
DTD1 is named in the same sentence as 12 diseases in open-access papers, as found by Europe PMC text mining. Sharing a sentence is not in itself a finding about the gene and the disease. The quoted sentences say what the papers report.
asthma (1 paper, 2017). "DTD1 also may be a risk factor for aspirin-intolerant asthma through a mechanism that promotes a pro-inflammatory phenotype." (PMID 28820441, 2017).
DTD1 also shares sentences with these, for which no sentence is quoted: melanoma (2 papers); breast carcinoma (1); epilepsy (1); glioma (1); hepatoma (1); lipoid proteinosis (1); lung carcinoma (1); ovarian dysfunction (1); Perrault syndrome (1); tumor (1); urothelial cell carcinoma (1).